TNFSF12-TNFSF13 (TNFSF12-TNFSF13 readthrough)
Synonyms: TWE-PRIL
Gene: Protein-coding gene on chromosome 17 (7,549,099 to 7,561,601, forward strand). Ensembl gene ENSG00000248871.
Genetic constraint (gnomAD): Loss-of-function variants: 28 observed, 43.69 expected, observed/expected ratio (o/e) 0.64, 90% interval 0.47 to 0.88. The upper end of that interval is the gene's LOEUF score, 0.88, which puts it in group 3 of 6, group 1 being the genes least tolerant of losing a copy. Missense variants: 413 observed, 399.97 expected, observed/expected ratio (o/e) 1.03, 90% interval 0.95 to 1.12. Synonymous variants: 177 observed, 158.78 expected, observed/expected ratio (o/e) 1.11, 90% interval 0.99 to 1.26.